FSD2 (fibronectin type III and SPRY domain containing 2)
Synonyms: SPRYD1; RP11-127F21
Tractability: No criterion of Open Targets' tractability assessment is met for any kind of drug.
Gene: Protein-coding gene on chromosome 15 (82,755,362 to 82,806,111, reverse strand). Ensembl gene ENSG00000186628.
Subcellular location: Nucleus; Sarcoplasmic reticulum; Cytoplasm, perinuclear region
Subcellular location (Human Protein Atlas): Cytosol
Gene Ontology:
Molecular function: protein binding
Cellular component: nucleus; perinuclear region of cytoplasm; sarcoplasmic reticulum
Genetic constraint (gnomAD): Loss-of-function variants: 67 observed, 74.78 expected, observed/expected ratio (o/e) 0.9, 90% interval 0.74 to 1.1. The upper end of that interval is the gene's LOEUF score, 1.1, which puts it in group 4 of 6, group 1 being the genes least tolerant of losing a copy. Missense variants: 910 observed, 926.28 expected, observed/expected ratio (o/e) 0.98, 90% interval 0.93 to 1.04. Synonymous variants: 358 observed, 334.9 expected, observed/expected ratio (o/e) 1.07, 90% interval 0.98 to 1.17.
Homologues: Orthologues: chimpanzee FSD2 (99% identical), macaque FSD2 (93% identical), pig FSD2 (87% identical), rabbit FSD2 (83% identical), rat Fsd2 (83% identical), mouse Fsd2 (79% identical), guinea pig FSD2 (79% identical), dog FSD2 (79% identical), tropical clawed frog fsd2 (48% identical). Paralogues in human: CMYA5 (31% identical), FSD1 (14% identical), FSD1L (13% identical).
Diseases named in the same sentence as FSD2 in open-access papers:
FSD2 is named in the same sentence as 5 diseases in open-access papers, as found by Europe PMC text mining. Sharing a sentence is not in itself a finding about the gene and the disease. The quoted sentences say what the papers report.
centronuclear myopathy (1 paper, 2023). Centronuclear myopathy (CNM) is an inherited neuromuscular disorder characterized by clinical features of a congenital myopathy and centrally placed nuclei on muscle biopsy. "This study suggests that Spegα and Spegβ display functional redundancy, identifies Esd, Cmya5 and Fsd2 as components of both cardiac dyads and skeletal muscle triads and lays the groundwork for the identification of new therapeutic targets for centronuclear myopathy." (PMID 37709832, 2023).
tumor (1 paper, 2023). "Taken together, higher or lower lnc‐FSD2‐31:1 in tumor cells activate/decrease CAFs autophagy through modulating EVs‐derived miR‐4736." (PMID 36727832, 2023). "In summary, we discovered that tumor‐derived lnc‐FSD2‐31:1 regulated autophagy and fibrosis of CAFs via EVs cargo miR‐4736." (PMID 36727832, 2023). "Collectively, these results suggest that lnc‐FSD2‐31:1 in tumor cells induces ATG7‐dependent autophagy and suppresses fibrosis in CAFs, which contribute to antitumor efforts in PDAC." (PMID 36727832, 2023). "Furthermore, our study revealed that tumor‐derived lnc‐FSD2‐31:1 restrained CAFs activation via EVs‐derived miR‐4736." (PMID 36727832, 2023).
FSD2 also shares sentences with these, for which no sentence is quoted: cancer (1 paper); cataract (1); Obesity (1).